IL6 (interleukin 6)
Diseases named in the same sentence as IL6 in open-access papers (continued):
Sharing a sentence is not in itself a finding about the gene and the disease.
rheumatoid arthritis (continued). "TCPTP silencing in rheumatoid arthritis synovial fibroblasts could also increase IL-6 production." (PMID 33692794, 2021). "Since anti-inflammatory drugs blocking the IL-6-receptor have been utilized in the second-line treatment of rheumatoid arthritis (RA) for more than a decade, it appears peculiar that research focusing on manipulation of IL-6 cascade in OA is scarce." (PMID 33482899, 2021). "Hence, QLY’s inhibition of IL-1β, IL-6, TNF-α, IL-2 and IFN-γ levels on AA rat serum might be part of the underlying mechanisms for QLY’s anti-rheumatoid arthritis effects." (PMID 34693865, 2021). "For diseases where tocilizumab has been effective (rheumatoid arthritis, polyarticular juvenile idiopathic arthritis, systemic juvenile idiopathic arthritis, and cytokine release syndrome), systemic inflammation is a feature of the disease and IL-6 levels are elevated." (PMID 34747368, 2021). "Cytokine inhibitors such as anti-TNF-α, anti-IL-17A, and anti-IL-6 have been used in other inflammatory-driven diseases such as rheumatoid arthritis (RA)." (PMID 34208697, 2021). "Probably the most significant experience with IL-6 blockade was gained in the treatment of rheumatic diseases, especially rheumatoid arthritis (RA), using an antibody against the IL-6 receptor, Tocilizumab." (PMID 34681685, 2021). "DC32, a dihydroartemisinin derivative, was found to significantly inhibit the transcription of chemokines (CXCL12 and CX3CL1) and IL-6 in rheumatoid arthritis (RA)." (PMID 34956376, 2021). "However, excessive production of TNF-α and IL-6 may lead to serious inflammatory disorders, including septic shock, rheumatoid arthritis, atherosclerosis, and cardiovascular diseases." (PMID 34071911, 2021). "IL6-RA has previously been shown to increase the frequency of infections in a randomized trial in rheumatoid arthritis." (PMID 33081828, 2020). "have reported that LQ ameliorates rheumatoid arthritis (RA) by reducing proinflammatory cytokines (IL-6) and blocking MAPK signalling." (PMID 32390832, 2020). "The clinical efficacy of specific interleukin-6 inhibitors has confirmed the central role of IL6 in rheumatoid arthritis (RA)." (PMID 33126846, 2020). "Numerous monoclonal antibodies (mAbs) are used clinically to target IL-6 signaling, for example, the anti-IL-6Rα mAbs tocilizumab and sarilumab, and the anti-IL-6 mAb siltuximab are used to treat several diseases including rheumatoid arthritis and kidney cancer." (PMID 32765502, 2020). "In addition, Th17 immune response-related pathways (LXR/RXR Activation, Role of Macrophages, Fibroblasts ad Endothelial Cells in Rheumatoid Arthritis, IL-6 Signaling, STAT3 Signaling, LPS/IL-1 Mediated Inhibition of RXR Function, and PPAR Signaling) were also activated." (PMID 33520738, 2020). "IL-6 signaling via α- and β-receptors (IL-6R and gp130) is an important biological process for cell differentiation and proliferation, tissue homeostasis, and, when dysregulated, crucial for the onset and progression of certain pathological conditions, such as rheumatoid arthritis and cancer." (PMID 32456348, 2020). "Particularly, IL-6 cytokine is critically involved in the progression of several inflammation-related/autoimmune diseases, such as rheumatoid arthritis (RA), liver and inflammatory bowel disease, and acute viral infection." (PMID 32485858, 2020). "The inflammatory pathways in which IL-6 is involved are also partly responsible of the development and progression of rheumatoid arthritis (RA), opening interesting perspectives in terms of therapy." (PMID 32718086, 2020). "In PsA and rheumatoid arthritis (RA) patients, IL-36α is upregulated in synovium-infiltrated plasma cells which stimulate the production of IL-6 and IL-8 from synovial fibroblasts." (PMID 31867327, 2019).
rheumatoid arthritis (continued). "Macrophages are a major source of inflammatory cytokines (e.g., TNFα, IL6, and IL1) implicated in the pathogenesis of inflammatory diseases such as rheumatoid arthritis (RA) and inflammatory bowel disease (IBD)." (PMID 31552020, 2019). "IL-6 is also a therapeutic target for many diseases, and the efficacy of anti-IL-6 receptor (IL-6R) Tocilizumab as a single therapy or in combination with anti-rheumatic drugs in the treatment of moderate to severe rheumatoid arthritis in adults has been demonstrated." (PMID 31970102, 2019). "A molecular mechanism of VD on CIA arthritis appears to be via a direct effect on T cells and/or indirectly on APCs by restraining Th17 cells differentiation via miR-124-mediated inhibition of IL-6 signaling, indicating that VD may have treatment implications in rheumatoid arthritis." (PMID 30792721, 2019). "TNF-α inhibitors were the second common group of drugs launched for rheumatoid arthritis, and these had a mean inflation-adjusted launch price of £898.53, though single examples of an interleukin (IL)-1 inhibitor, an inhibitor of T-cell co-stimulation and IL-6 inhibitors were priced even higher." (PMID 31061053, 2019). "Sirukumab, a high-affinity human monoclonal antibody that selectively binds to interleukin-6, has demonstrated efficacy in the treatment of rheumatoid arthritis (RA) in global phase 1 and phase 2 studies." (PMID 29514712, 2018). "Elevated levels of IL-6 and its soluble receptor (IL-6sR) have been observed in both rheumatoid arthritis (RA) and OA." (PMID 29867478, 2018). "However, anabolic side effects of anti-IL6 therapies are commonly reported in rheumatoid arthritis patients, including increased body weight and dyslipidaemia, suggesting that under steady state conditions IL6 is essential for a proper control of metabolic functions." (PMID 30158466, 2018). "After observation of a drastic clinical effect of TCZ on Castleman disease, which is a typical inflammatory disease caused by IL-6 overproduction, TCZ was shown to have significant effects on rheumatoid arthritis (RA) and juvenile idiopathic arthritis (JIA)." (PMID 30423923, 2018). "Interleukin-6 (IL-6) is an inflammatory cytokine with an important role in the pathogenesis of rheumatoid arthritis (RA)." (PMID 29041951, 2017). "Furthermore, circulating plasmablasts could induce the differentiation of Tfh cells via producing IL-6 in patients with rheumatoid arthritis, and IL-6 blockade reduced the population of Tfh cells." (PMID 28360886, 2017). "In this regard, the plasma levels of MCP-1, IL-6, and TNF-α could be used as surrogate biomarkers in clinical trials evaluating autoimmune disorders that are associated with elevated levels of these cytokines, such as rheumatoid arthritis and psoriasis." (PMID 28546852, 2017). "Interleukin 6 (IL-6) signaling plays a key role in the pathophysiology of rheumatoid arthritis (RA) and is inhibited by sarilumab, a human monoclonal antibody blocking the IL-6 receptor alpha (IL-6Rα)." (PMID 27716324, 2016). "In humans, the pathological effects of IL-6 overproduction are specifically inhibited by tocilizumab, a commercialized monoclonal antibody directed against IL-6R, approved in 2009 for the treatment of rheumatoid arthritis, and in 2011 for the treatment of systemic juvenile idiopathic arthritis." (PMID 26782790, 2016). "In rheumatoid arthritis (RA), synovial fibroblasts (SF) secrete large amounts of IL-6, IL-8 and matrix metalloproteinases (MMPs) which are crucial for cartilage destruction." (PMID 27158245, 2016).
rheumatoid arthritis (continued). "A host of proinflammatory cytokines, namely, tumor necrosis factor (TNF-α), IL-1β, and IL-6, are involved in the pathogenesis of rheumatoid arthritis (RA) and are crucial to determine progression of chronic joint inflammation and concomitant bone erosion." (PMID 25784780, 2015). "It is an activator of acute phase responses and the overproduction of IL-6 was seen in a variety of chronic autoimmune and inflammatory diseases, including rheumatoid arthritis (RA) and inflammatory bowel disease." (PMID 26075907, 2015). "The pleiotropic cytokine interleukin-6 (IL-6) plays an important role in the pathogenesis of different diseases, including rheumatoid arthritis (RA)." (PMID 25994180, 2015). "The use of corticosteroids, an anti-inflammatory drug which reduces the production of (IL-1 and IL-6), led to osteoporosis in patients with rheumatoid arthritis (RA)." (PMID 26925890, 2015). "Tocilizumab (TCZ), which is a humanized antibody against the interleukin 6 (IL-6) receptor, inhibits signaling mediated by IL-6 and was first approved to treat rheumatoid arthritis (RA) in Japan in 2008." (PMID 25880658, 2015). "Interleukin 6 (IL-6) is an inflammatory cytokine that is elevated in several autoimmune and inflammatory disorders, including rheumatoid arthritis (RA)." (PMID 25974216, 2015). "For example, bone resorption can be upregulated due to cytokines such as TNFα and IL-6 in systemic inflammatory diseases such as rheumatoid arthritis (RA)." (PMID 26041376, 2015). "Previous studies have shown that inflammatory cytokines induce MMPs, which may be a pivotal role for inflammatory cytokines such as IL-6 and IL-8 in the pathogenesis of diseases such as rheumatoid arthritis, chronic obstructive pulmonary disease, and corneal ulceration." (PMID 25390332, 2014). "IL-6 is one of the most important mediators of fever and of the acute-phase response, and plays a key role in several inflammatory diseases including rheumatoid arthritis, systemic juvenile idiopathic arthritis, systemic lupus erythematosus, ankylosing spondylitis, etc.." (PMID 23840548, 2013). "Therefore, we can conclude that although blockade of IL-6 and IL-6 signaling have been shown to be effective in treating several inflammatory diseases (e.g., tocilizumab for rheumatoid arthritis and inflammatory bowel disease), its effect in patients with DM should be limited." (PMID 24082909, 2013). "Finally, IL-6 may be a potential therapeutic target as humanized anti–IL-6 receptor antibody, tocilizumab, has been used to target the IL-6 pathway in rheumatoid arthritis, Castleman disease, and systemic lupus erythematosus." (PMID 24216293, 2013). "For example, inhibition of IL-6 by the first anti-IL-6 antibody, tocilizumab, has been shown to completely block TF-dependent thrombin generation in experimental endotoxemia, and tocilizumab will be of special future interest as it has been approved for rheumatoid arthritis." (PMID 22518344, 2012). "Regardless, the interlocking of the IL-6 and BAFF pathways may have therapeutic ramifications, since an IL-6 antagonist (tocilizumab) is already approved for the treatment of one autoimmune inflammatory disorder (rheumatoid arthritis) and, in principle, could be beneficial in others as well." (PMID 21897850, 2011). "IL-6, a pleiotropic cytokine, has a destructive role in rheumatoid arthritis (RA), contributing to joint inflammation as well as joint pain." (PMID 21858242, 2011). "Biologic agents that target tumor necrosis factor (TNF), B cells, T cells, or, most recently, interleukin-6 (IL-6) have emerged as effective treatments for patients with rheumatoid arthritis (RA)." (PMID 21884601, 2011). "Importantly, overproduction of IL-6 from synovial cells is critically involved in the pathogenesis of rheumatoid arthritis, a chronic, debilitating disease in which articular inflammation and joint destruction are accompanied by systemic manifestations including anaemia, fatigue and osteoporosis." (PMID 20633276, 2010).
rheumatoid arthritis (continued). "Interestingly, some other cytokines such as IL-1 and IL-6 that were found to play important roles in many inflammatory diseases such chronic obstructive pulmonary disease, inflammatory bowel disease and rheumatoid arthritis, were also decreased in CC10-Smad7 mice." (PMID 20405019, 2010). "A role for IL-6 in rheumatoid arthritis has been proposed based upon the ability of the cytokine to activate inflammatory responses and osteoclastogenesis and is supported by positive clinical data obtained with the anti-IL-6 mAb tocilizumab in this patient population." (PMID 18234077, 2008). "In a disease such as rheumatoid arthritis (RA), the pathological roles of pro-inflammatory cytokines such as TNFα, interleukin (IL)-1β, and IL-6 have been demonstrated." (PMID 18493620, 2008). "Locally produced proinflammatory cytokines such as tumor necrosis factor-α, interleukin (IL)-1, and IL-6 play a pivotal role in the pathology of rheumatoid arthritis (RA)." (PMID 17511858, 2007). "Rheumatoid arthritis therapy focuses on targeting the immune system’s signaling molecules, such as tumor necrosis factor (TNF) and interleukin 6 (IL-6), which are involved in the progression of the disease." (PMID 40565171, 2025). "As an example, the binding of PlGF to Flt-1 in patients with rheumatoid arthritis stimulated the production of proinflammatory cytokines, including TNF-α and IL-6 in monocytes, enhancing inflammation." (PMID 40800007, 2025). "The marked reduction in TNF-α and IL-6 is particularly noteworthy, as these cytokines are central to the pathology of chronic inflammatory diseases such as endometriosis, rheumatoid arthritis (RA), and inflammatory bowel disease (IBD)." (PMID 40958911, 2025). "Whereas in rheumatoid arthritis, PVT1 knockdown suppressed IL-1β and IL-6 expression, consistent with our findings of significantly reduced IL-6 expression in the SLE + si-Pvt1 group, while also activating apoptosis in fibroblast-like synoviocytes." (PMID 40493320, 2025). "It significantly reduced the expression of IL-1, IL-6, IL-17, and TNF-α in rats with rheumatoid arthritis (p < 0.05)." (PMID 40006536, 2025). "In rheumatoid arthritis (RA), key molecular mechanisms include the activation of proinflammatory cytokines such as TNF-α and IL-6, which drive inflammation and joint damage." (PMID 40755762, 2025). "In patients with rheumatoid arthritis, the inflammatory response triggers the excessive secretion of cytokines, such as tumor necrosis factor-alpha (TNF-α) and interleukin-6 (IL-6)." (PMID 40538801, 2025). "The alcohol extract of FC down-regulated IL-6 and TNF-α in rheumatoid arthritis and osteoarthritis rat models and inhibited ear edema induced by xylene." (PMID 41515139, 2025). "IL‐17 plays a key role in the progression of rheumatoid arthritis in the TMJ, amplifying inflammation by stimulating the release of other pro‐inflammatory cytokines (such as TNF‐α, IL‐6, and IL‐1β), chemokines, and matrix metalloproteinases." (PMID 41006957, 2025). "The case of IL-6 illustrates this complexity: while its inhibition shows therapeutic potential in conditions like rheumatoid arthritis and potentially IPF, IL-6 also plays essential roles in tissue regeneration and metabolism." (PMID 40820275, 2025). "Previous studies have shown that YY1 regulates IL6 expression in a variety of conditions, including LPS-stimulated BV2 microglial cells, and in vivo models for rheumatoid arthritis and prostate cancer." (PMID 40143084, 2025). "In patients with rheumatoid arthritis, rituximab significantly reduced serum concentrations of CRP, RF, anti-CCP, IL-2, IL-6, IL-7, IL-10, and ESR." (PMID 41057909, 2025). "Notable examples include IgE‐dependent activation by mast cells, expression of cell‐adhesion molecules, activation of NKCs, and worsening of clinical symptoms related to rheumatoid arthritis (RA) in the morning, correlating with the daily rhythm of the proinflammatory cytokine IL‐6." (PMID 41476991, 2025).
rheumatoid arthritis (continued). "Among these, IL-1β, IL-6, and TNF-α play a substantive role in both rheumatoid arthritis and osteoarthritis." (PMID 40491903, 2025). "Filgotinib, which has been approved for use in rheumatoid arthritis (RA) and ulcerative colitis, is a JAK1 preferential inhibitor that suppresses downstream signals of IL-6, and it was anticipated that filgotinib would also be effective in iMCD." (PMID 39958406, 2025). "Rheumatoid arthritis results in an increase in serological biomarkers such as ACPA, CRP, IL-1β, IL-6, and TNF-α." (PMID 40136507, 2025). "In rheumatoid arthritis (RA), a female-predominant disease similar to AD, elevated intracellular levels of miR-19 exacerbate the production of pro-inflammatory interleukin 8 (IL-8) and IL-6 by primary fibroblast-like synoviocytes." (PMID 40869991, 2025). "Rheumatoid arthritis patients are characterized by elevated levels of pro-inflammatory cytokines such as TNF-α, IL-6, IL-1β, and CRP, which reflect heightened inflammatory activity." (PMID 40709173, 2025). "A study on rheumatoid arthritis showed that high-dose silibinin significantly reduced inflammatory markers (ESR, IL-8, IL-6, TNF-α, anti-CCP) and increased Hb, IL-10, and IL-2, compared to placebo." (PMID 39850538, 2025). "Within the synovium of individuals with rheumatoid arthritis, STEAP4 inhibits inflammation by blocking the activity of inflammatory cytokines (specifically IL-6 and IL-8), impeding cell proliferation, and inducing apoptosis of fibroblast-like synoviocytes." (PMID 39176391, 2024). "It reduces pro-inflammatory cytokines, i.e., interleukin-6 (IL-6), and tumor necrosis factor-α (TNF-α) production in a rheumatoid arthritis rat model." (PMID 38390130, 2024). "Studies found that participants with rheumatoid arthritis who experience a higher burden of CVD due to hypertension benefited from supplementation with a natural anti-inflammatory compound that reduced CRP, IL6, and TNFα." (PMID 39558500, 2024). "Rheumatoid arthritis is characterized by systemic inflammation (high levels of proinflammatory cytokines–TNF, IL-1, IL-6, matrix metalloproteinases-MMP, circulating autoantibodies) that disrupt bone metabolism." (PMID 38672734, 2024). "Another study showed that a bs-Ab targeting TNF-α and IL-6 (TNF-α × IL-6)successfully inhibited CXCR-13 activity in both in vitro and in vivo models of rheumatoid arthritis." (PMID 39609700, 2024). "The inflammatory targets that mediate rheumatoid arthritis mainly include (TNF, PTPN11, IL6, etc.); the main targets that mediate RA oxidative stress are NOS3; the targets that mediate the destruction of extracellular matrix tissue in RA mainly include (MMP9, MMP2, ANXA5, etc.)." (PMID 38238321, 2024). "Kang and colleagues investigated the role of 3′SL in inflammation connected to rheumatoid arthritis and observed that cotreatment with IL-1β and 3′SL in THP-1 cells also reduced IL-1β, IL-6, and TNF mRNA and protein expression." (PMID 39325548, 2024). "IL-6 trans-signaling also promotes secretion of CXLC8 and CCL2 by rheumatoid arthritis synoviocytes, a cell type related to mesothelial cells." (PMID 39114667, 2024). "In rheumatoid arthritis (RA), in vivo studies have reported immunosuppressive properties of EVs that inhibit the proliferation of T lymphocytes and reduction in pro-inflammatory cytokines IL-6, TNF-α, and IL-1β." (PMID 38397121, 2024). "Anakinra is a recombinant human IL-1 receptor antagonist (IL-1ra) authorized for use in treating rheumatoid arthritis and other illnesses characterized by inflammation and has been found to reduce inflammatory markers such as CRP, ferritin, D-dimers, and IL-6." (PMID 39493146, 2024). "Specifically, it decreases the production of several cytokines, including IL-17, IL-6, IL-10, and TNF-α, as well as IFN-γ in rheumatoid arthritis (RA) patients and induces Tregs in certain experimental models." (PMID 38791521, 2024).